ALOX5 (arachidonate 5-lipoxygenase)
Diseases named in the same sentence as ALOX5 in open-access papers (continued):
Sharing a sentence is not in itself a finding about the gene and the disease.
meningitis (1 paper, 2023). A disorder characterized by acute inflammation of the meninges of the brain and/or spinal cord. "However, we could not find a sufficient number of studies that showed an association between infectious meningitis and ALOX5." (PMID 38115295, 2023). "A heat map was created to visualize the concentrations of DEFA1, GFAP, ALOX5, and S100B in the meningitis and healthy control groups." (PMID 38115295, 2023). "Here, the levels of ALOX5, S100B, DEFA1, and GFAP in the CSF of patients with meningitis caused by different infectious agents were compared to those of healthy controls." (PMID 38115295, 2023). "DEFA1, GFAP, ALOX5, and S100B successfully distinguished patients with meningitis from controls." (PMID 38115295, 2023). "According to the heat map, ALOX5, S100B, DEFA1, and GFAP levels were partially increased in the meningitis group versus controls." (PMID 38115295, 2023). "ROC curve analysis was performed to differentiate the variation in ALOX5, S100B, DEFA1, and GFAP between groups to distinguish meningitis patients from healthy individuals and from different types of meningitis." (PMID 38115295, 2023). "Comparison of CSF levels of ALOX5, S100B, DEFA1, GFAP in the groups with infectious meningitis and in the healthy control groups." (PMID 38115295, 2023). "This study showed that the parameters ALOX5, S100B, DEFA1, and GFAP could discriminate between meningitis patients and healthy controls, although with varying degrees of reliability." (PMID 38115295, 2023).
myeloma (1 paper, 2011). "As DZNep induce apoptosis in myeloma cells in large parts through attenuating elevated expression of ALOX5, we wanted to see if ALOX5 is also aberrantly expressed in human MM." (PMID 21720561, 2011).
myeloproliferative neoplasm (1 paper, 2025). A clonal hematopoietic stem cell disorder, characterized by proliferation in the bone marrow of one or more of the myeloid (i.e., granulocytic, erythroid, megakaryocytic, and mast cell) lineages. "To collect evidence that supports this idea, we considered our previous findings that the Alox5 gene plays an essential role in functional regulation of LSCs for both PV and CML, two different types of myeloproliferative neoplasms driven by JAK2V617F and BCR-ABL, respectively." (PMID 41226393, 2025).
ocular hypertension (1 paper, 2024). Abnormally high intraocular pressure. "The results demonstrate that Alox5AP (5-lipoxygenase activating protein, FLAP), which is a cofactor required for full 5-LOX enzymatic activity, was significantly upregulated at 2 and 4 weeks, while there was no change in the levels of Alox5 in response to ocular hypertension." (PMID 38610040, 2024).
oral squamous cell carcinoma (1 paper, 2020). "Using the Toruner dataset (20 patient samples), we found that the expression of IFIT1, (p = 2.76 × 10−8) and ALOX5 (p = 0.0019) genes were high in oral squamous cell carcinoma (OSCC) compared to normal squamous cells." (PMID 32961854, 2020).
Peritoneal Fibrosis (1 paper, 2023). Disorder characterized by a wide range of structural changes in PERITONEUM, resulting from fibrogenic or inflammatory processes. "Among them, MMP2, BAX, ADORA3, HIF1A, PIM1, CA12, and ALOX5 exhibited higher expression in the peritoneum with encapsulating peritoneal sclerosis compared with those in the control, which might be crucial targets of baicalein against peritoneal fibrosis." (PMID 37266145, 2023).
renal carcinoma (1 paper, 2024). A carcinoma arising from the epithelium of the renal parenchyma or the renal pelvis. "RCC also demonstrates upregulation of ALOX5, TBXAS1, and cysLTR1, supporting literature on the role of TBXA2 in upregulating renal cancer and 5-LOX in progressing carcinogenesis." (PMID 39062733, 2024).
skin infection (1 paper, 2018). An inflammatory process affecting the skin, caused by bacteria, viruses, parasites, or fungi. "We first measured the mRNA transcript levels for Alox5 (the gene that encodes 5-LO), Ltb4r1 (the gene that encodes BLT1), and Ltb4r2 (BLT2) during MRSA skin infection." (PMID 30102746, 2018). "At 1 day post-MRSA skin infection, the expressions of Alox5 and Ltb4r1, but not Ltb4r2, were significantly enhanced in the skin of infected mice compared to naïve mice skin." (PMID 30102746, 2018).
Splenomegaly (1 paper, 2021). Abnormal increased size of the spleen. "It remains unclear for the moment why the Alox5-KI mice develop splenomegaly when taken through this experimental protocol." (PMID 34677413, 2021).
uveitis (1 paper, 2020). An inflammatory process affecting a part of or the entire uvea. "To examine whether downregulation of S1pr1 under conditions of LXA4 deficiency can be detected in uveitis-relevant T cells, we assessed S1pr1 expression in CD4+ T cells from inguinal lymph nodes of EAU-challenged Alox5-/- and WT mice by RT-PCR." (PMID 32118582, 2020).
tumor (153 papers, 2009 to 2026). "In vivo studies further revealed that ectopic ALOX5 expression in AGS cells reversed the tumor suppressive effect caused by JMJD3 deficiency." (PMID 41184226, 2025). "ALOX5 is the most abundant of the six human lipoxygenases in NB and has been implicated as a tumor suppressor." (PMID 38672672, 2024). "We first identified the transformative tumor-associated MCs subpopulation C2 ALOX5+ MCs within CC, which was at a critical stage of tumor differentiation and impacted the progression of CC." (PMID 39224598, 2024). "Further analysis of MCs subgroups identified the distinct presence of the C2 ALOX5+MCs subgroup in CC, suggesting its potential role as a tumor-associated MCs subgroup with transformative effects on immunity and inflammation." (PMID 39224598, 2024). "In vivo efficacy study of targeting tumor-associated macrophages in combination with targeting ALOX5." (PMID 38124204, 2023). "In line with these in vitro data, reduced ALOX5 expression was associated with the significant impairment of xenograft tumor growth in tumor-bearing mice." (PMID 38090559, 2023). "The SAA/ALOX5 ratio strongly correlated with TANs and was significantly increased in tumours harbouring an oncogenic KRAS mutation." (PMID 34203378, 2021). "Expression was next evaluated in tumours harbouring multiple mutations, where ALOX5 expression was significantly reduced in tumours with a KRAS and LKB1 mutation." (PMID 34203378, 2021). "Similarly to COX2, the ALOX5 gene, encoding for arachidonate 5-lipoxygenase, has been associated with a high expression of further tumor-promoting genes involved in mutagenesis and immunosuppression." (PMID 34281208, 2021). "Bioluminescence imaging demonstrated that the reduction of tumor sizes and growth rate in JMJD3-deficient AGS xenografts was counteracted by ectopic ALOX5 expression." (PMID 41184226, 2025). "The expression of ALOX5 was also validated in independent patients with tumours originating from the C3 subtype using the IHC method." (PMID 38804617, 2024). "High expression levels of ALOX5, indicative of abundant macrophage infiltration, have been identified in tumor samples of gastric thyroid, pancreatic, renal, endometrial, and urothelial cancers." (PMID 38612771, 2024). "CD4 and 5-LOX (ALOX5) mRNA levels were significantly more expressed in tumour samples than in normal tissues in both GBM and LGG." (PMID 38816839, 2024). "Inhibition of ALOX5 in tumor cells leads to varied impacts on gene expression profiles and cellular functions depending on the cell type." (PMID 38612771, 2024). "CD4 and ALOX5 gene expression level significantly differed between tumour samples when compared to normal brain tissue in both GBM and LGG." (PMID 38816839, 2024). "Regarding the input pathways in target cells, the receptors associated with C2 ALOX5+MCs were primarily CD99, SELE, and SPP1, while the receptors related to tumor cells included TWEAK, CEACAM, and CD96." (PMID 39224598, 2024). "ALOX5 affected tumor occurrence and development through catalyzing the metabolism of arachidonic acid and was closely associated with poor prognosis in various malignant tumors." (PMID 39224598, 2024). "ALOX5 was also upregulated in the high-risk group, which can enhance the production of LBT4 in neutrophils, promoting tumour cell metastasis." (PMID 38365809, 2024). "The circular plot displayed the number and strength of cell-cell interactions between C2 ALOX5+MCs as the source and tumor cells as the targets." (PMID 39224598, 2024). "Expression of 5-LOX/ALOX5 in the GBM tumor is found in macrophage and microglial cells as well as in other cells, such as cancer cells." (PMID 36765904, 2023).
tumor (continued). "Mechanically, LTB4, a metabolite downstream of ALOX5, recruited M2 macrophages to migrate around tumor cells by binding to BLT1/BLT2 and activating the PI3K pathway, which ultimately lead to the promotion of ICC progression." (PMID 38124204, 2023). "SELP and ALOX5 are highly expressed in some tumours and cancer cell lines, inducing cancer cell proliferation and inhibiting apoptosis." (PMID 37816387, 2023). "In a similar number of tumor types, there is a reduction in the expressions of 5-LOX/ALOX5 and FLAP/ALOX5AP." (PMID 36765904, 2023). "We found that Alox5 was significantly elevated in the GM:F344 tumor tissues (up 2.5-fold) compared to the GM:LEW group." (PMID 37458451, 2023). "The research showed that ALOX5, one of extracellular vesicle derived mRNA transcripts, was found specific to urine and tumor tissue samples and defined disease-specific extracellular vesicle biomarkers in liquid biopsy patient samples." (PMID 38090559, 2023). "Utilizing IHC, we assessed ALOX5 protein expression levels in ccRCC tumor tissues and normal tissues." (PMID 38090559, 2023). "In summary, our findings indicated that the ALOX5 rs702365 [G] > [C] change has a tumor suppressive role in CRC by decreasing ALOX5 transcription." (PMID 37144561, 2023). "We found that the expression levels of EFEMP2, EHD2, FSTL3 and ALOX5 were decreased in tumor tissues, whereas COL3A1 was significantly increased in tumor samples." (PMID 37291533, 2023). "For instance, ALOX5 contributes to the recruitment and activation of macrophages thereby adding to the role of macrophages in a dynamically changing tumor environment." (PMID 35962453, 2022). "Consecutively, the disseminated tumor cells are colonized by a variety of mechanisms facilitating metastatic spread, including hypoxia, chemokine-dependent, and arachidonate 5-lipoxygenase (ALOX5)-dependent leukotriene synthesis to recruit neutrophils." (PMID 34885082, 2021). "In the HPA database, NRAS, STEAP3, and ALOX5 proteins are significantly expressed in tumor tissues, but the difference in the expression of ZFP36 and GABARAPL1 proteins is not obvious." (PMID 34868262, 2021). "Taken together, these observations suggest that acquisition of the KRAS driver mutation represents a molecular abnormality that will drive increased SAA expression in a tumour microenvironment where ALOX5 expression is reduced." (PMID 34203378, 2021). "Analysis of individual patient's tumor/normal ratio of Alox5 and 5‐HETE showed that all patients who displayed significant upregulation of ALOX5 also demonstrated higher level of 5‐HETE, except patients #6, #10, #11, #21, #26, #36, and #49." (PMID 34121352, 2021). "Analysis of ALOX5 gene expression in this TCGA dataset was also very consistent with our findings, where ALOX5 levels were uniformly reduced in tumours relative to normal tissue." (PMID 34203378, 2021). "To investigate if differences in Alox5 protein levels between normal and tumor gastric tissues are significant, we performed both ELISA (quantitative) and IHC (qualitative) analyses." (PMID 34121352, 2021). "Consistently, we found that ALOX5 was upregulated in the tumour samples, while AGXT, PTGER3, and SLC12A3 were downregulated in the tumour samples." (PMID 32144299, 2020). "In contrast, ALOX5 demonstrated higher mRNA expression levels in tumours, and patients with high levels of ALOX5 expression had a low survival rate." (PMID 32144299, 2020). "Colony forming/replating and bone marrow transplantation (BMT) assays showed that Alox5 exhibited a moderate anti-tumor effect both in vitro and in vivo." (PMID 28500307, 2017). "Collectively, our work shows that ALOX5 plays a moderate anti-tumor role and functions as a drug sensitizer, with a therapeutic potential, in MLL-rearranged AML." (PMID 28500307, 2017).
tumor (continued). "Several groups have examined the role of ALOX5 pathway in carcinogenesis and have shown that it plays an important role in promoting tumor growth and survival." (PMID 21720561, 2011). "It is plausible that ALOX5, through its lipid metabolites, may activate signaling pathways that support tumor self-renewal and therapy resistance." (PMID 41184226, 2025). "In addition, we chose C2 ALOX5+MCs as the source and tumor cells as the targets to study the interactions between MCs and tumor cells." (PMID 39224598, 2024). "ALOX5 and its by-product metabolites, such as 5-HETE and 5-oxo-ETE, promote tumour cell proliferation that may cause a pro-malignancy path." (PMID 39457550, 2024). "However, it cannot be excluded that another ALOX5 metabolite is also equally involved in stimulating 5-oxo-ETE synthesis by tumor cells, resulting in OXER1-mediated enhanced migration." (PMID 38202807, 2023). "Indeed, we found that both signaling cascades suppress the ALOX5 gene in a number of other tumor cell lines." (PMID 36849252, 2023). "They showed that four tumor-specific mRNA (ALOX5, RBL2, VEGFA, TLK2) present in EVs (defined as present in tumor-derived-, urine- and plasma-EVs, but absent in tumor-adjacent tissue EVs) may be used as RCC biomarkers in the future." (PMID 35629194, 2022). "Among these significant genes of IL-4 signaling are CFLAR, ALOX5, PMAIP1, EGR1, NCF2, SLC39A8, and PEG10 which have been reported to be associated with tumor progression or chemotherapy-drug resistance through effecting proliferation and apoptosis in previous studies." (PMID 33506057, 2021). "Increased SAA expression and decreased ALOX5 expression resulted in a significant increase in the SAA/ALOX5 ratio in KRAS mutated tumours but not in KRAS wild-type tumours." (PMID 34203378, 2021). "As subpopulations of tumour-associated immune cells expressed ALOX5AP and ALOX5 (encoding the enzymes that catalyse the leukotriene synthesis), the ligand for wild-type CysLT2R may be produced by immune cells in the inflammatory microenvironment." (PMID 33588787, 2021). "The pattern of 5‐HETE level in normal and tumor was similar to ALOX5 as shown by the scatter plot." (PMID 34121352, 2021). "Conditioned medium from pre-metastatic lung neutrophils contains high level of leukotrienes (LTs), the products of the arachidonate 5-lipoxygenase (ALOX5) enzyme, which promote tumor sphere growth in vitro and increase the metastatic initiation potential of cancer cells in vivo." (PMID 33101283, 2020). "Therefore, our results suggest that Alox5 exerts its anti-tumor and drug sensitizing effects in MLL-rearranged AML through suppressing the Stat and K-Ras signaling pathways." (PMID 28500307, 2017). "The anti-tumor role of Alox5 implies a therapeutic potential in treating AML." (PMID 28500307, 2017). "Thus, our data indicated that Alox5 exhibited a moderate anti-tumor effect in the maintenance of MLL-rearranged AML and restrains leukemic cell infiltration." (PMID 28500307, 2017). "Therefore, the ALOX5 gene plays a role in tumor cell proliferation." (PMID 37372393, 2023). "Moreover, arachidonate 5-lipoxygenases (ALOX5) could enhance the function of macrophages in the changing tumor environment." (PMID 36118882, 2022). "Hence, the tumour microenvironment is likely reducing ALOX5 mRNA in leukocytes." (PMID 34203378, 2021).